UMOD (uromodulin)
Description:
[Uromodulin]: Functions in biogenesis and organization of the apical membrane of epithelial cells of the thick ascending limb of Henle's loop (TALH), where it promotes formation of complex filamentous gel-like structure that may play a role in the water barrier permeability (Probable). May serve as a receptor for binding and endocytosis of cytokines (IL-1, IL-2) and TNF. Facilitates neutrophil migration across renal epithelia. [Uromodulin, secreted form]: In the urine, may contribute to colloid osmotic pressure, retards passage of positively charged electrolytes, and inhibits formation of liquid containing supersaturated salts and subsequent formation of salt crystals (By similarity). Protects against urinary tract infections by binding to type 1 fimbriated E.coli. Binds to bacterial adhesin fimH which mediates the stable formation of bacterial aggregates, prevents the binding of E.coli to uroplakins UPK1A and UPK1B which act as urothelial receptors for type I fimbriae, and allows for pathogen clearance through micturation. Also promotes aggregation of other bacteria including K.pneumoniae, P.aeruginosa and S.mitis and so may also protect against other uropathogens.
Synonyms: THP; ADMCKD2; ADTKD1; FJHN; HNFJ; HNFJ1; MCKD2; THGP
Tractability: Antibody: UniProt places it where antibodies can reach, with high confidence; UniProt predicts a signal peptide or a membrane-spanning region; its Gene Ontology location is reachable by antibodies, with medium confidence.
Gene: Protein-coding gene on chromosome 16 (20,331,549 to 20,356,402, reverse strand). Ensembl gene ENSG00000169344.
Subcellular location: Apical cell membrane; Basolateral cell membrane; Cell projection, cilium membrane; Secreted (Uromodulin, secreted form)
Pathways (Reactome):
Metabolism of proteins: Asparagine N-linked glycosylation
Gene Ontology:
Molecular function: IgG binding; protein binding; calcium ion binding
Biological process: antibacterial innate immune response; defense response to Gram-negative bacterium; gene expression; heterophilic cell-cell adhesion; leukocyte cell-cell adhesion; neutrophil migration; protein localization to extracellular region; cellular defense response; negative regulation of cell population proliferation; metanephric ascending thin limb development; metanephric distal convoluted tubule development; metanephric thick ascending limb development; monoatomic ion homeostasis
Cellular component: apical plasma membrane; basolateral plasma membrane; cell surface; cilium; extracellular exosome; extracellular region; membrane; mitotic spindle pole body; spindle pole; extrinsic component of membrane; Golgi lumen; ciliary membrane; endoplasmic reticulum; plasma membrane
Genetic constraint (gnomAD): Loss-of-function variants: 65 observed, 64.41 expected, observed/expected ratio (o/e) 1.01, 90% interval 0.82 to 1.24. The upper end of that interval is the gene's LOEUF score, 1.24, which puts it in group 5 of 6, group 1 being the genes least tolerant of losing a copy. Missense variants: 764 observed, 802.28 expected, observed/expected ratio (o/e) 0.95, 90% interval 0.9 to 1.01. Synonymous variants: 397 observed, 338.43 expected, observed/expected ratio (o/e) 1.17, 90% interval 1.08 to 1.27.
Gene-disease validity (ClinGen):
ClinGen rates the evidence that UMOD causes each of these diseases.
autosomal dominant medullary cystic kidney disease with or without hyperuricemia (autosomal dominant): Definitive. A genetic kidney disease that causes progressive loss of kidney function caused by mutations in the genes encoding uromodulin (UMOD), hepatocyte nuclear factor-1β (HNF1B), renin (REN), or mucin-1 (MUC1).
Homologues: Orthologues: chimpanzee UMOD (99% identical), macaque UMOD (94% identical), pig UMOD (84% identical), dog UMOD (81% identical), guinea pig UMOD (78% identical), rat Umod (77% identical), rabbit UMOD (76% identical), mouse Umod (75% identical). Paralogues in human: GP2 (42% identical), OIT3 (23% identical), UMODL1 (20% identical), ZPLD1 (14% identical), TECTB (9% identical).
Diseases named in the same sentence as UMOD in open-access papers:
UMOD is named in the same sentence as 142 diseases in open-access papers, as found by Europe PMC text mining. Sharing a sentence is not in itself a finding about the gene and the disease. The quoted sentences say what the papers report.
chronic kidney disease (67 papers, 2011 to 2025). Impairment of the renal function secondary to chronic kidney damage persisting for three or more months. "The THP, also known as uromodulin, is associated with kidney function along with graft survival, CVDs, glucose metabolism, end-stage renal disease, systemic inter-organ signaling, and overall mortality." (PMID 39409080, 2024). "Recent studies suggest that the presence of a high level of uromodulin (in urine or serum) is independently associated with a reduced risk of incident acute and chronic kidney disease, progression of kidney disease, and cardiovascular and mortality outcomes." (PMID 37242477, 2023). "The presence of collagen fragments, α1-microglobulin, β2MG, A1AT, and uromodulin appear to be promising biomarkers for detecting patients with DM2 at high risk of developing chronic kidney disease." (PMID 37675359, 2023). "In a prospective German chronic kidney disease study, elevated serum uromodulin levels were linked to a reduced risk of adverse kidney events over time." (PMID 37835820, 2023). "Five variants associated also with chronic kidney disease progression mapped to genes with functional in-silico evidence (UMOD, SPATA7, GALNTL5, TPPP)." (PMID 35716955, 2022). "Genome-wide association studies discovered variants of uromodulin that are associated with chronic kidney diseases and hypertension." (PMID 36378920, 2022). "The encoded kidney-specific protein uromodulin is highly abundant in urine and related to chronic kidney disease, hypertension, and pathogen defense." (PMID 35446786, 2022). "Consistently, our study team reported lower levels of serum uromodulin were independently associated with a higher risk of incident end-stage kidney disease (ESKD) among patients with chronic kidney disease (CKD)." (PMID 34828293, 2021). "A GWAS identified the major allele of SNP rs4293393 is correlated with uromodulin gene expression, urinary excretion, chronic kidney disease, and the development of salt‐sensitive hypertension." (PMID 34363725, 2021). "Several studies have shown that urinary uromodulin was independently associated with a rapid decline in renal function and the incidence of end-stage renal disease (ESRD)." (PMID 34869624, 2021). "The potential utility of serum and urine uromodulin measurement in kidney transplant recipients (KTRs) has been studied, showing an association of lower serum uromodulin levels with progression to end-stage renal disease and graft failure." (PMID 32764335, 2020). "A heterozygous missense variant (c.674C > G; p.T225R) in UMOD was found in this boy, his older brother with the same phenotype and his mother with hyperuricaemia, gout and chronic kidney disease." (PMID 32847529, 2020). "The renal clinical phenotype caused by UMOD mutation is characterized by dominant inheritance, chronic kidney disease due to chronic tubulointerstitial nephritis, hyperuricemia, gout, and, occasionally, renal cysts (19–, 21)." (PMID 29513881, 2018). "Human GWAS and Mendelian genetic studies have linked polymorphic variants and mutations in the human uromodulin gene (UMOD) with chronic kidney disease." (PMID 29595914, 2018). "In this study, we investigated the association between a common variant rs13333226 in the promoter region of UMOD gene and end stage renal disease (ESRD)." (PMID 27938332, 2016). "Subsequently, the same research group described that uromodulin (UMOD) variant affected risk of chronic kidney disease by providing protection against KSD." (PMID 24886237, 2014). "Tamm-Horsfall glycoprotein (THP) is abundant in urine, and in humans it is encoded by the UMOD (uromodulin) gene, which is associated with chronic kidney disease and blood pressure." (PMID 23894628, 2013). "Previous studies have indicated that UMOD mutations contribute to FJHN/MCKD2 and that promoter variants of the UMOD gene are associated with eGFR, blood pressure, plasma uric acid level, and incidence of chronic kidney disease." (PMID 23990922, 2013).
chronic kidney disease (continued). "One study found that elevated urinary uromodulin level was a risk factor for future incidence of chronic kidney disease." (PMID 23990922, 2013). "In recent genetic association studies, common variants including rs12917707 in the UMOD locus have shown strong evidence of association with eGFR, prevalent and incident chronic kidney disease and uromodulin urinary concentration in general population cohorts." (PMID 22947327, 2012). "In addition to their role in urinary stone risk, UMOD variants have been implicated in urinary acidification, renal function, and the development of chronic kidney disease." (PMID 39156495, 2024). "Changes in uromodulin levels in urine and serum began to be associated with kidney function disorders, cardiovascular diseases, and hypertension but also with prognosis in chronic kidney disease." (PMID 39061561, 2024). "On the other hand, genome-wide association studies (GWAS) revealed that common variants in the UMOD promoter region, which drive variable expression levels of uromodulin, are linked with increased risks of chronic kidney disease, calcium stones and hypertension in the general population." (PMID 31444371, 2019). "Causes for end-stage renal disease in the total cohort and urinary uromodulin quartiles." (PMID 31124979, 2019). "This gene encodes the renal tubular protein uromodulin, and we have previously observed that higher urinary uromodulin concentration is associated with an increased odds of chronic kidney disease as well as with rs4293393, a UMOD SNP in linkage disequilibrium with rs12917707 (r2 = 1)." (PMID 22044751, 2011). "Prior studies have found that rare mutations in the UMOD gene cause at least two forms of autosomal dominant hereditary kidney disease that progress into end-stage renal disease (ESRD) (familial juvenile hyperuricemicnephropathy and a form of medullary cystic kidney disease)." (PMID 21235779, 2011). "For example, one previous study found that higher levels of urinary uromodulin were associated with a lower risk of eGFR decline, a lower risk of incident chronic kidney disease (CKD), and a lower risk of mortality in the aged population." (PMID 39409080, 2024). "An increasing body of evidence indicates that elevated levels of uromodulin, whether in the urine or serum, are independently associated with a reduced risk of developing acute and chronic kidney disease, as well as the progression of kidney disease, cardiovascular disease, and mortality." (PMID 37835820, 2023). "In various genome-wide association studies, common allelic UMOD promoter variants were identified to be associated with increased risk for complex trait diseases like chronic kidney disease (CKD), hypertension and kidney stones." (PMID 25409434, 2014). "Genome-wide association studies have also revealed that common variants in the promoter region of the UMOD gene are associated with chronic kidney disease (CKD), glomerular filtration rate (GFR), kidney stone formation and hypertension." (PMID 23990922, 2013). "An immunoregulatory function of UMOD is also suggested by our observations in the Snx model of chronic kidney disease, where low UMOD serum levels and Umod gene expression in the kidney correlated with increased inflammation." (PMID 40087735, 2025). "Mutations in the UMOD gene can cause ADTKD, while common polymorphisms in this gene are also associated with multiple disorders such as chronic kidney disease (CKD), hypertension, and cardiovascular diseases." (PMID 40770350, 2025). "A promising biomarker for evaluating kidney function and metabolic status in chronic kidney disease (CKD) is serum uromodulin (sUmod)." (PMID 39456940, 2024). "Uromodulin levels were positively associated with estimated GFR and inversely associated with proteinuria, as well as independently associated with End-Stage Renal Disease (ESRD) or rapid loss of estimated GFR." (PMID 38785547, 2024).
chronic kidney disease (continued). "There have been several excellent recent publications reviewing uromodulin biology and function, with a particular focus on chronic kidney disease (CKD)." (PMID 39259220, 2024). "This linkage is comprehensible given the recognized association between chronic kidney disease (CKD) and cardiovascular events, alongside the established role of uromodulin in salt-sensitive hypertension." (PMID 39049957, 2024). "In nonrheumatic patients, several studies have identified low serum uromodulin levels in patients with chronic kidney disease (CKD)." (PMID 36301848, 2022). "SDS-PAGE of urine proteins showed a reduction in uromodulin and a larger number of low molecular mass protein bands, comparable to cats with chronic kidney disease." (PMID 35891483, 2022). "It is hypothesized that uromodulin entering the renal interstitium, either by basolateral secretion or urinary back-leakage in damaged tubuli, interacts with and stimulates cells of the immune system and, thereby, causes inflammation and progression of chronic kidney disease." (PMID 35455664, 2022). "Genome-wide association studies (GWAS) have shown that common variants in the promoter of the UMOD gene that encodes uromodulin are associated with estimated glomerular filtration rate (eGFR) and the risk of chronic kidney disease (CKD) and hypertension in the general population." (PMID 31863061, 2019). "UMOD is an abundant kidney‐specific protein that has garnered renewed attention in recent years due to growing evidence of important linkages with human chronic kidney disease." (PMID 29595914, 2018). "Altogether, 35 individuals from 18 families were found to have ten distinct UMOD mutations (three novel), making up 1% of patients with CKD 3–5, 2% of patients with end-stage renal disease, 9% of inherited kidney diseases and 56% with ADTKD." (PMID 30376835, 2018). "Reduced urinary and serum concentrations of uromodulin are found in persons with interstitial fibrosis or tubular atrophy in the course of chronic kidney disease." (PMID 28777303, 2017). "Uromodulin (UMOD) gene mutation causes autosomal dominant Uromodulin-Associated Kidney Disease (UAKD), which in turn leads to end-stage renal disease." (PMID 27489562, 2016). "We aimed to explore associations of several single nucleotide polymorphisms (SNPs) detected by genome-wide association studies in uromodulin (UMOD) gene with phenotypes and prognosis of chronic kidney disease (CKD) among 2731 Chinese patients with CKD stage 1–4." (PMID 34828293, 2021). "Recent studies suggest that the level of uromodulin in the urine could be used as a biomarker of the development of chronic kidney diseases." (PMID 32722141, 2020). "The uromodulin concentration and expression of six selected miRNAs (miR-29c, miR-126, miR-146a, miR-150, miR-155, and miR-223) were determined in the serum of 100 KTRs with stable graft function and chronic kidney disease of all five stages." (PMID 32764335, 2020). "Some families with UMOD mutations have a milder clinical course, without hyperuricemia and gout and milder manifestations of chronic kidney disease (12,13, )." (PMID 29513881, 2018). "Studies on the association of serum uromodulin and outcomes of chronic kidney disease (CKD) are lacking." (PMID 30454063, 2018). "Hence, in the current study, we measured the serum uromodulin levels and investigated the association of serum uromodulin with kidney function and outcomes of CKD in a large, multicenter prospective cohort study of CKD patients, the Chinese Cohort Study of Chronic Kidney Disease (C-STRIDE)." (PMID 30454063, 2018). "Recent studies suggest that uromodulin plays an important role in chronic kidney diseases." (PMID 27113631, 2016). "Recent data showed that uromodulin plays an important role in chronic diseases of the kidney." (PMID 26673890, 2015).
chronic kidney disease (continued). "Furthermore, decreased UMOD expression has been observed in end-stage renal disease, in kidney neoplasms and in cysts from autosomal dominant polycystic kidney disease." (PMID 25202906, 2014). "Uromodulin might play a two-faceted role in chronic kidney disease: the damage of renal tubules may result in decreased synthesis of uromodulin and uromodulin itself also involved in the pathogenesis of kidney disease progression." (PMID 23990922, 2013). "The aim of our research was to select a more appropriate form of uromodulin for the diagnosis of early stages of chronic kidney disease (CKD)." (PMID 39061561, 2024). "In the context of chronic kidney disease (CKD) of different etiologies, urinary uromodulin levels tend to decrease significantly and are strongly correlated with variations in estimated glomerular filtration rate." (PMID 37835820, 2023). "Studies have indicated that the prevalence of hyperfiltration, a precursor to chronic kidney disease, is higher among individuals with obesity and this could serve as an alternative explanation to our findings of increased UMOD expression in those that have a high BMI." (PMID 33768217, 2021). "In early phase of AP, serum uromodulin positively correlated with eGFR (independently of sex and age) and negatively with serum creatinine and cystatin C; however, the correlations were much weaker as compared to what has been observed in chronic kidney disease." (PMID 31366007, 2019). "Patients with chronic kidney disease (CKD) have reduced urinary uromodulin levels secondary to tubular damage." (PMID 31065383, 2019). "CUBN, UMOD, and SHROOM3 were identified by human GWAS as being associated with albuminuria, kidney function, and chronic kidney disease (CKD)." (PMID 26219736, 2015). "Recent studies have suggested that uromodulin may play a role in chronic kidney diseases." (PMID 23990922, 2013). "However it is still unclear whether uromodulin influences the progression of chronic kidney disease." (PMID 23990922, 2013). "As none of the carriers of the T469M minor allele had end-stage renal disease, our results suggest that either T469M may not be a causal variant for Mendelian forms of uromodulin-associated disease, or it is a mild one with a modest effect on renal survival." (PMID 22693617, 2012). "Uromodulin is also involved in the progression of chronic kidney disease (CKD); decreased urinary uromodulin levels tend to correlate with reduced nephron mass and may serve as predictors of CKD progression and mortality." (PMID 40519162, 2025). "Proteins with high disease scores (76–100% confidence) for both hypertension and chronic kidney disease included angiotensinogen (AGT), albumin (ALB), apolipoprotein L1 (APOL1), and uromodulin (UMOD)." (PMID 38402394, 2024). "The reduced number of tubular cells seen in chronic kidney disease (CKD) due to interstitial fibrosis/tubular atrophy (IF/TA) is paralleled by the reduced urinary and serum concentrations of uromodulin." (PMID 32764335, 2020). "Recently, serum uromodulin concentrations have been shown to reflect the mass of remaining renal tissue and strongly positively correlate with GFR values across all stages of chronic kidney disease." (PMID 31366007, 2019). "In addition, UMOD gene mutations cause UMOD-associated kidney disease (UAKD), and polymorphisms in the UMOD gene are strongly linked to chronic kidney disease (CKD)." (PMID 31725735, 2019). "Our study in Caucasian patients didn’t find an association of UMOD gene variant rs12917707 with IgAN, nor with the progression of IgAN towards end stage renal failure, in spite of the known association of this variant with chronic kidney disease of mixed aetiologies." (PMID 25163389, 2014).